RETN (resistin)
Diseases named in the same sentence as RETN in open-access papers (continued):
Sharing a sentence is not in itself a finding about the gene and the disease.
dermatomyositis (5 papers, 2012 to 2023). Dermatomyositis (DM) is a type of idiopathic inflammatory myopathy characterized by evocative skin lesions and symmetrical proximal muscle weakness. "In patients with myositis-specific anti-Jo-1 antibody and, particularly, in dermatomyositis patients, elevated resistin levels associated with disease activity and muscle enzymes." (PMID 22577940, 2012). "In this study, we report for the first time an association between increased levels of serum resistin and the disease activity of patients with inflammatory myopathies, particularly in anti-Jo-1 positive and dermatomyositis patients." (PMID 22577940, 2012). "The results of this study indicate that higher levels of serum resistin are associated with inflammation, higher global disease activity index and muscle injury in patients with myositis-specific anti-Jo-1 antibody and patients with dermatomyositis." (PMID 22577940, 2012). "In dermatomyositis-associated ILD, patients with higher resistin levels also had decreased DLCO and more often had a rapidly progressive ILD." (PMID 37759429, 2023). "To investigate the role of adipokines in adult and pediatric patients with newly diagnosed dermatomyositis (DM), we analyzed peripheral blood and skeletal muscle gene expression of four adipokines: visfatin, leptin, adiponectin and resistin." (PMID 25918482, 2015). "Moreover, increased serum adiponectin and resistin levels were detected in dermatomyositis patients, but lower serum leptin levels were observed." (PMID 28076515, 2016). "In addition, resistin, another adipocyte-derived hormone observed to be elevated in Hispanic individuals with higher body adiposity, has been implicated in SSc-ILD pathogenesis and dermatomyositis-associated ILD." (PMID 37759429, 2023). "In the current study, we aimed to assess resistin mRNA levels in the peripheral blood mononuclear cells (PBMCs) of dermatomyositis patients with interstitial lung disease (DM-ILD) and their correlation with disease activity." (PMID 35592858, 2022). "Furthermore, in patients with dermatomyositis, serum resistin levels significantly correlated with MYOACT (r = 0.667, P = 0.001), creatine kinase (r = 0.739, P = 0.001) and myoglobin levels (r = 0.791, P = 0.0003) and showed a trend towards correlation with CRP levels (r = 0.447, P = 0.067)." (PMID 22577940, 2012).
endometriosis (5 papers, 2019 to 2024). The growth of functional endometrial tissue in anatomic sites outside the uterine body. "IL-1β, IL-23, and resistin were highly present in the patients’ FFs, and their increase showed a tendency toward endometriosis severity." (PMID 39000283, 2024). "It has been demonstrated that resistin, a member of the adipokine family, is also elevated in the PF of patients with endometriosis, and that the expression of resistin significantly increases in the ectopic endometrial tissues of patients with endometriosis." (PMID 34072419, 2021). "Serum resistin and IL-23 levels were positively correlated with endometriosis stages III-IV." (PMID 39000283, 2024). "Thus, we hypothesized that higher resistin levels in endometrioma fluid is similar to visfatin/NAMPT is an indicator of local inflammation in endometriosis." (PMID 38075048, 2023). "In this study, evaluation of serum level of leptin, resistin, homocysteine, CA125, and TAC was selected to find their possible alteration in an induced autograph model of endometriosis and following treatment with curcumin." (PMID 30806992, 2019). "This study explores the changes of serum levels of Cancer Antigen 125 (CA125), leptin, resistin, homocysteine, and total antioxidant capacity (TAC) in a rat model of endometriosis and the effect of curcumin treatment on these factors." (PMID 30806992, 2019). "No significant alteration in the level of serum resistin noticed in endometriosis groups (treated & non‐treated) compare to the control group." (PMID 30806992, 2019). "Our results show that visfatin/NAMPT and resistin may be locally secreted in endometrioma related to inflammation regardless of the stage of endometriosis." (PMID 38075048, 2023). "Our hypothesis is supported by studies that showed higher resistin levels in peritoneal fluid of women with than without endometriosis and higher resistin mRNA and protein levels in ectopic endometrial tissue of patients with endometriosis compared to normal eutopic endometrial tissue." (PMID 38075048, 2023).
helminth infections (5 papers, 2015 to 2023). "Together, these studies suggest that human resistin is a detrimental cytokine that is expressed in multiple helminth infections, mediates pathogenic inflammation, and delays parasite clearance." (PMID 25568944, 2015). "The authors found that human resistin was both up-regulated in the period after helminth infection, and that this increased level of resistin was associated with an enhanced Th1 immune response, increased worm burden and impaired parasite clearance." (PMID 26295162, 2015). "Targeting resistin may therefore provide new approaches to host-directed treatment strategies for helminth infection and amelioration of the associated immune-mediated pathology." (PMID 25568944, 2015). "Targeting the resistin/proinflammatory cytokine immune axis may provide new diagnostic or treatment strategies for helminth infection and associated immune-mediated pathology." (PMID 25568944, 2015). "Human resistin has been reported to be detrimental in helminth infection as it promotes the production of pro-inflammatory cytokines while impairing monocyte migration and monocyte-driven parasite killing." (PMID 31147868, 2019). "A recent paper has explored the relationship between the adipokine resistin, and multiple helminth infections." (PMID 26295162, 2015). "Although many studies have shown that LPS can induce resistin expression both in vitro and in vivo, our data implicates resistin expression as a common innate response to multiple helminth infections." (PMID 25568944, 2015). "A plausible mechanism to explain this observation involving the adipokine resistin has been described, and further study into the complex relationship between helminth infection, immunity and metabolic disease would be of value." (PMID 26295162, 2015). "Together, these studies identify human resistin as a detrimental factor induced by multiple helminth infections, where it promotes proinflammatory cytokines and impedes parasite clearance." (PMID 25568944, 2015). "In summary, our studies contribute to the growing evidence of the pleiotropic effects of human resistin in several human diseases, and demonstrate a critical function for this protein in helminth infection." (PMID 25568944, 2015). "To examine the role of human resistin in helminth infection, we employed transgenic mice that express human resistin." (PMID 25568944, 2015). "Here, we identify an important immunoregulatory function for human resistin in helminth infection." (PMID 25568944, 2015). "To study the function of human resistin in helminth infection, we utilized mice in which the human resistin gene along with its entire regulatory region was inserted using a bacterial artificial chromosome onto a murine resistin knockout background (hRetnTg+)." (PMID 25568944, 2015). "Given that we have previously observed the induction of RELM proteins in various helminth infections of mice, we hypothesized that human resistin expression may be an indicator of multiple helminth infections." (PMID 25568944, 2015). "In human studies with filarial-infected individuals, Brugia malayi antigen increased resistin mRNA in human monocytes, particularly when these monocytes were isolated from filarial-infected humans, prompting our investigation of the function of human resistin in helminth infection." (PMID 25568944, 2015). "It is likely that the difference in expression pattern between murine resistin, which is expressed in adipose tissue, and human resistin, which is expressed by monocytes/macrophages, accounts for the functional differences between murine and human resistin during helminth infection." (PMID 25568944, 2015).
hypertriglyceridemia (5 papers, 2014 to 2023). A laboratory test result indicating elevated triglyceride concentration in the blood. "Here we show that resistin SNV (−420C/G) is linked with hypertriglyceridemia, selected metabolic parameters, and the preference to consume fried food." (PMID 36501122, 2022). "We applied three multivariable logistic regression models to evaluate the risk of hypertriglyceridemia in relation to the studied resistin variant." (PMID 36501122, 2022). "We aimed to evaluate the relationship between resistin (−420C/G) single nucleotide variant (SNV) and metabolic parameters and preference for fried food consumption in hypertriglyceridemia." (PMID 36501122, 2022). "In addition, the circulating concentrations of three hormones that regulate metabolism, resistin, leptin, and glucose-dependent insulinotropic polypeptide, were reduced by TIMEx consumption, which may be involved in its effect to prevent hypertriglyceridemia." (PMID 35208189, 2022).
infarction (5 papers, 2009 to 2024). A localised pathological necrosis of tissue resulting from obstruction of the blood supply usually by a thrombus, an embolus, or vascular torsion. "In the present study, we demonstrated for the first time that infarction was associated with an increased resistin expression via the GIP-dependent pathway, subsequently leading to an increased NGF expression both in vivo and ex vivo." (PMID 26811539, 2016). "In our study, subjects with lacunar and atherothrombotic infarction, but not cardioembolic infarction, had greater resistin concentrations." (PMID 19922611, 2009).
influenza (5 papers, 2020 to 2024). An acute viral infection of the respiratory tract, occurring in isolated cases, in epidemics, or in pandemics; it is caused by serologically different strains of viruses (influenzaviruses) designated A, B, and C, has a 3-day incubation period, and usually lasts for 3 to 10 days. "The concentrations of the RETN, MMP8, LCN2, ELANE and BPI in plasma tended to be higher in influenza patients than healthy donors." (PMID 33448094, 2021). "Among them, RETN (resistin), also known as C/EBP-ε, is a critical transcription factor and was highly up-regulated in severe influenza patients (p < 0.0001)." (PMID 32066441, 2020).
liver dysfunction (5 papers, 2013 to 2024). "We investigated serum concentrations of total adiponectin (Acrp30), leptin, and resistin in patients with chronic alcohol abuse and different grades of liver dysfunction, as well as ALD complications." (PMID 24259947, 2013). "Therefore, the objective of the present study was to determine serum concentrations of total adiponectin (Acrp30), leptin, and resistin in patients with chronic alcohol abuse and different grades of liver dysfunction." (PMID 24259947, 2013). "One of the studies could not demonstrate an association of resistin with liver dysfunction scores, but here, resistin was higher in patients with cholestasis and patients with renal impairment." (PMID 28661458, 2017). "Elevated levels of RETN gene expression in COVID19-ACEi were positively correlated with the estimated glomerular filtration rate, which is used to assess kidney function), and alanine aminotransferase, which can indicate liver dysfunction." (PMID 36817759, 2022).
Neonatal sepsis (5 papers, 2023 to 2025). Systemic inflammatory response to infection in newborn babies. "This study highlights the link between elevated serum resistin levels and increased mortality risk in neonatal sepsis, supported by strong multivariate analysis, indicating an independent predictive role." (PMID 38562275, 2024). "Additionally, resistin correlates with higher chances of mechanical ventilation and prolonged hospitalization, suggesting its potential as a prognostic marker for early identification of high-risk neonatal sepsis cases." (PMID 38562275, 2024). "The current evidence suggests that the RETN level is a valuable biomarker for detecting paediatric and neonatal sepsis." (PMID 40416430, 2025). "Although resistin has been studied extensively in the context of adult inflammatory diseases, its role in neonatal sepsis remains a relatively uncharted territory." (PMID 38562275, 2024). "Moreover, the role of resistin in neonatal sepsis remains relatively unexplored, and the study's exclusive focus on resistin overlooks the potential contributions of other biomarkers." (PMID 38562275, 2024). "The study investigating serum resistin in neonatal sepsis is subject to certain limitations." (PMID 38562275, 2024). "Recent studies have demonstrated that novel biomarkers, such as resistin, haptoglobin, and sTREM-1, could be applied for clinical prognostic identification of neonatal sepsis, but their expensive and time-consuming disadvantage hinders widespread implication in neonatal sepsis." (PMID 40687411, 2025).
pulmonary arterial hypertension (5 papers, 2019 to 2025). Pulmonary arterial hypertension (PAH) is a group of diseases characterized by mean pulmonary artery pressure >20 mmHg and elevated pulmonary arterial resistance leading to right heart failure. "Development of pulmonary arterial hypertension (PAH) was linked to role of resistin-induced angiogenesis and immune response." (PMID 30806766, 2019). "Right ventricular tissue of pulmonary hypertension patients demonstrates increased resistin expression, as does right ventricular tissue from rats in which pulmonary hypertension was induced by monocrotaline treatment." (PMID 41515891, 2025). "Our previous work suggested that resistin has the potential to be used as a biomarker and therapeutic target for human pulmonary arterial hypertension." (PMID 32609743, 2020). "Moreover, overexpression of cardiac human resistin produced right ventricular dilatation and dysfunction, suggesting that resistin can contribute to right ventricular dysfunction in response to pulmonary hypertension." (PMID 41515891, 2025). "In addition, increased levels of resistin were found in SSc patients with pulmonary arterial hypertension and digital vasculopathy." (PMID 33839992, 2021).
Renal insufficiency (5 papers, 2009 to 2022). A reduction in the level of performance of the kidneys in areas of function comprising the concentration of urine, removal of wastes, the maintenance of electrolyte balance, homeostasis of blood pressure, and calcium metabolism. "Serum resistin levels are markedly elevated in patients with renal insufficiency, indicating a strong impact of eGFR on resistin levels, as previously reported." (PMID 34886472, 2021).
systemic sclerosis (5 papers, 2018 to 2022). A chronic disorder, possibly autoimmune, marked by excessive production of collagen which results in hardening and thickening of body tissues. "In conclusion, an increased serum level of resistin associated with increased endothelin-1 and fractalkine level and decreased adiponectin level may indicate a significant role of the adipose tissue in the development and progression of vascular abnormalities in patients with systemic sclerosis." (PMID 31667578, 2020). "The aim of this study was to investigate the serum concentration of metabolic adipose tissue factors: adiponectin, resistin, leptin and endothelial proteins: endothelin-1, fractalkine and galectin-3 in patients with systemic sclerosis." (PMID 31667578, 2020).
tuberculosis (5 papers, 2015 to 2024). A chronic, recurrent infection caused by the bacterium Mycobacterium tuberculosis. "Taken together, we consider analyzing the association between khat addiction, tuberculosis and resistin levels." (PMID 26448186, 2015). "Tuberculosis being a disease of immune modulation has a varied spectrum of complex interplay of proinflammatory molecules, resistin is one of them." (PMID 26448186, 2015). "Contrastingly, resistin levels significantly correlate with bacterial load among the khat addicted tuberculosis patients (P<0.0006)." (PMID 26448186, 2015). "To assess whether increased resistin levels among the khat abuser has any effect on severity of tuberculosis, we examined the resistin levels between khat addicted and non khat addicted tuberculosis patients." (PMID 26448186, 2015). "Another study in patients without T2D, found higher concentrations of serum resistin in TB patients than in healthy controls, and this concentration diminishes during 6 months of treatment with a standard anti-tuberculosis treatment." (PMID 31637222, 2019). "tuberculosis infection to assess whether khat facilitates the growth of mycobacterium in lungs This study will be first of its kind to assess a correlation between resistin level, among khat addicted and non addicted subjects and tuberculosis patients with and without khat addiction." (PMID 26448186, 2015).
Alzheimer disease (4 papers, 2017 to 2025). A progressive, neurodegenerative disease characterized by loss of function and death of nerve cells in several areas of the brain leading to loss of cognitive function such as memory and language. "The authors claimed that resistin is a regulatory marker of inflammation and considered resistin being a predictor of Alzheimer’s disease caused by activation of the immune system." (PMID 28421328, 2017).
aneurysm (4 papers, 2018 to 2022). Bulging or ballooning in an area of an artery secondary to arterial wall weakening. "Pro-inflammatory cytokines such as resistin, leptin, and TNFα have been shown to induce changes leading to the formation of aneurysms, while adiponectin is the only known compound that is secreted by adipose tissue and limits the development of aneurysms." (PMID 35745168, 2022). "Another compound secreted by adipose tissue as well as monocytes/macrophages that are perceived to contribute to aneurysms is resistin." (PMID 35745168, 2022). "The secretion of resistin from atheroma-derived macrophages was suggested because of the colocalization of resistin and CD68 in the staining of human aneurysms and the higher mRNA resistin expression in cultured macrophages than in controls." (PMID 30584543, 2018). "Intragroup analysis for group 2 showed increased Pecam-1, CXCL8, resistin, osteopontin and decreased levels of leptin, pentraxin-3 in KD with aneurysms as compared to patients without CAA (non-significant)." (PMID 36096831, 2022). "Intragroup analysis for group 3 patients revealed elevated VEGF-A, CXCL8, Leptin, Pentraxin-3, resistin in patients with CAA as compared to KD without aneurysms while pecam-1, endoglin and osteopontin were comparable in both." (PMID 36096831, 2022).
Autoimmunity (4 papers, 2013 to 2023). The occurrence of an immune reaction against the organism's own cells or tissues. "In this study, we therefore investigated whether human resistin levels are affected by T1DM associated with autoimmunity/inflammation." (PMID 24072088, 2013). "Taken together it was concluded that elevation of visfatin and resistin in T2DM may lead to impaired thyroid function by inducing thyroid-autoimmunity responses." (PMID 36830883, 2023). "Thus, it appears that both heparanase and resistin may play a common and co-operative role in inflammation and autoimmunity." (PMID 24465803, 2014).